YAP1 (Yes1 associated transcriptional regulator)
Diseases named in the same sentence as YAP1 in open-access papers (continued):
Sharing a sentence is not in itself a finding about the gene and the disease.
cancer (continued). "Drugs that target the oncogenic function of the Hippo pathway downstream effectors YAP1 and TAZ are therefore possible tools to compensate for the loss of Hippo-kinases, and to phenocopy RASSF1A function within cancer cells with either the loss of RASSF1A or defects in the Hippo pathway." (PMID 34831091, 2021). "Finally, YAP1 activation is also described as a bypass mechanism to KRAS inactivation in cancers driven by oncogenic mutant KRAS signaling." (PMID 34685695, 2021). "YAP1 expression was upregulated or downregulated in various cancers." (PMID 34150844, 2021). "Thus, the role of YAP1 in cancer development remains controversial, and further study of the clinical significance of YAP1 expression is needed." (PMID 34257617, 2021). "In addition, ACTL6A stabilizes the YAP1/TAZ pro-cancer transcriptional regulators, which are part of the Hippo signaling cascade, and reduces expression of the p21Cip1 tumor suppressor." (PMID 34689163, 2021). "The discrepancies in levels of YAP1 expression in cancer from different databases may be attributable to the data collection approaches and underlying mechanisms pertinent to different biological properties." (PMID 34257617, 2021). "Lamar and colleagues have reported that increased SRC activity may be the driver of high activity of YAP1/TAZ in human cancers." (PMID 34693980, 2021). "Interestingly, in global gene expression analyses, YAP1 was found to transactivate genes that specifically promote cancer cell motility and consequently metastatic formation." (PMID 34395416, 2021). "For example, cancers that dysregulate the Hippo pathway may be more sensitive to suppression of YAP1 activity." (PMID 34150758, 2021). "Clinically, YAP1 is used as a target for cancer drug development." (PMID 34660259, 2021). "As senescent cells may contribute to disease recurrence after cancer therapy, the potential clinical application of YAP1 inhibition together with RASSF1A-activating drugs may also require sequential targeting of p21 to shift senescent cells into apoptosis." (PMID 34831091, 2021). "The increased activity of YAP1 in human cancers may be attributed to YAP1 gene amplification and gene fusion as well as the dysregulation of other components of the Hippo pathway." (PMID 34150758, 2021). "Notably, recent studies also reported that upregulation of YAP1 is involved in cancer metabolism and mTOR activation by altering specific genes involved in metabolic pathways." (PMID 34003553, 2021). "It’s also been claimed that YAP1 could behave as a tumor suppressor gene in some cancers, which would be a poor prognostic factor." (PMID 34953494, 2021). "Previous studies have shown that abnormal expression of YAP1 occurs in many malignant tumors." (PMID 34530822, 2021). "YAP1 activity in tumors results in cancer progression and drug resistance." (PMID 34446793, 2021). "YAP1 in cancer cells also confers resistance to certain drugs." (PMID 34150844, 2021). "According to the previous data, YAP1 served as an oncogene in GC, and targeting YAP1 was effective to restrain cancer progression, which were supported by our data that YAP1 was high-expressed in GC tissues and cells, and GC patients with high-expressed were prone to have a worse prognosis." (PMID 33975517, 2021). "In addition to the GEPIA, UALCAN database was further used to evaluate the clinical significance of YAP1 expression in pan-cancers." (PMID 34257617, 2021). "YAP1 positively regulates drug resistance and cancer cell stemness." (PMID 34715859, 2021). "Recent studies have demonstrated a high activity of SFKs and YAP1/TAZ in cancers." (PMID 34693980, 2021). "The heterogeneity of YAP1 expression among cancer types and databases may be attributed to differences in data collection methods and analytical approaches." (PMID 34150844, 2021).
cancer (continued). "YAP1-involved ASAP1-IT1/miR-509-3p axis promoted NSCLC progression by regulating cancer cell stemness, and targeting this signaling pathway could be is a promising therapeutic strategy to overcome NSCLC stemness." (PMID 34715859, 2021). "Thus, our study provided evidence of the carcinogenesis of YAP1 in human cancers and new insights into its mitochondrial-regulatory network of YAP1." (PMID 34257617, 2021). "YAP1 has been considered as an oncogene in multiple cancers including NSCLC." (PMID 34715859, 2021). "Thus, given the emerging oncogenic roles of YAP1 in cancer metabolism and KRAS mutant tumors, we also aimed to investigate the role of YAP1 in the regulation of AATs expression and function in KRAS mutant CRC cells." (PMID 34003553, 2021). "Interestingly, recent observation revealed YAP1 was involved in the anti-cancer effect of OXPHOS inhibitors (metformin plus LW6)." (PMID 34257617, 2021). "Indeed, it has been shown previously that SFKs, namely Src, can stimulate YAP1/TAZ expression in cancer cells of various types." (PMID 34693980, 2021). "Our findings demonstrate that lncRNAs coregulate both the YAP1 and mTORC1 pathways in cancer." (PMID 34462427, 2021). "The expressions of cancer stem cell-related genes, Sox2 and Oct4, were decreased by siRNA of YAP1." (PMID 34445421, 2021). "Moreover, YAP1 is overexpressed at a high frequency in many common human cancers, and can directly drive cancer development in mouse models." (PMID 34206989, 2021). "Notably, the copy-number events exhibiting higher prevalences in young adult cancers were mainly amplifications, including YAP1 (FDR = 0.027) and MYC (FDR = 6.94E-4), significantly associated with young adult CESC and OV, respectively." (PMID 34788626, 2021). "On the other hand, VGLL4’s ability to disrupt YAP1–TEADs interaction indicates that peptide mimics of VGLL4 could potentially be useful for suppressing cancers driven by Hippo pathway dysregulation." (PMID 34150758, 2021). "This pattern of expression suggests that YAP1 may act as an oncosuppressor in parathyroid tumorigenesis, at variance with reports in most common human cancers." (PMID 33670622, 2021). "YAP1 can also directly drive cancer development in mouse models." (PMID 34206989, 2021). "Bioinformatics analysis showed that miR-509-3p could target the 3′UTR of YAP1, which is an oncogene in the Hippo signaling pathway involved in human cancers." (PMID 34715859, 2021). "High YAP1 expression is particularly prominent in cancer stem cells." (PMID 34199594, 2021). "In these cases, YAP1 expression was obviously stronger in recurrent cancer than in primary cancer." (PMID 33420363, 2021). "Given the crucial role of CAFs within the TME, targeting these cells might be a promising therapeutic approach to reduce the invasiveness and stemness of carcinoma cells regulated by YAP1." (PMID 34680267, 2021). "YAP1 is a potent oncogene of the Hippo signaling pathway and is amplified in various human cancers." (PMID 32154166, 2020). "Therefore, through regulation of GTSE1, YAP1 facilitates epithelial-to-mesenchymal transition (EMT) in cancer cells." (PMID 32390875, 2020). "Previous studies have indicated dynamics of YAP1 expression could promote malignant transformation, enhance the expansion of several cancer stem-like cells and chemotherapy drug resistance." (PMID 33123286, 2020). "Because gene network analysis strongly suggested that the SOH signature may be associated with immune-related pathways, we further analyzed genomic data to determine whether YAP1/TAZ plays a role in regulation of the host immune response to cancer cells." (PMID 32717825, 2020). "In addition, since YAP1 is active in cancer cells, it can regulate a variety of cancer genes or form complexes with them and then jointly regulate the downstream target genes." (PMID 32066485, 2020).
cancer (continued). "Yes Associated Protein 1 (YAP1) is a transcriptional regulator that plays a crucial role in regulating cellular proliferation and migration in cancer and was identified as another direct target for miR-205 through bioinformatics analyses utilizing TargetScan and miRanda prediction tools." (PMID 32854238, 2020). "In addition, the present study also aimed to assess if YAP1 is involved in the anti-cancer effect of metformin plus LW6." (PMID 31897243, 2020). "Our results demonstrate that BRD4 is a critical regulator of Hippo/YAP1 signaling and that BRD4 inhibitor JQ1 represents a new class of inhibitor of Hippo/YAP1 signaling, primarily targeting YAP1 high and therapy‐resistant cancer cells enriched with cancer stem cell properties." (PMID 32175692, 2020). "lncRNA-MAYA is involved in the regulation of DC-STAMP indirectly as it mediates the activation of yes-associated protein 1 (YAP1), which upregulates CTGF expression, leading to elevated cancer cell-induced osteoclastogenesis and bone resorption." (PMID 32908541, 2020). "More interestingly, many inhibitory immune checkpoint genes, such as CTLA4, PD-1, and PD-L2, were upregulated in the SOH subgroup, suggesting that YAP1/TAZ may induce resistance of cancer cells to host immune response in GBM." (PMID 32717825, 2020). "In cells, the YAP1 protein can form a protein complex with TEADs, which contains a DNA binding domain to bind to DNA for transcriptional regulation of gene expression for cell proliferation and wound healing, as well as for cancer development and progression." (PMID 32827244, 2020). "YAP1 can promote cancer cell proliferation, migration and invasion through multiple mechanisms." (PMID 32541093, 2020). "YAP1 confirmed to be an oncogene in some cancers through plenty of researches." (PMID 32918541, 2020). "Moreover, between more than thirty cancer types, the gene expression profile of squamous cell carcinomas (SCCs) had the highest level of YAP1/TAZ expression." (PMID 32722184, 2020). "To assess whether the inhibitor of YAP1/TEAD interaction verteporfin can affect HER2-positive cancer-cell growth and proliferation, we performed a pharmacological assay to evaluate its effects on both sensitive and trastuzumab-resistant cell lines." (PMID 32365528, 2020). "Hippo/YAP1 signaling is a major regulator of organ size, cancer stemness, and aggressive phenotype." (PMID 32175692, 2020). "We believe that, as one of the indicators of the biological behaviour of malignant tumours, YAP1 is increased in the stroma of the PCa and there could be a certain reference value for the diagnosis of cancer." (PMID 32066485, 2020). "Our bioinformatics analyses also suggested a link between NEK1 and YAP1 in different cancers." (PMID 33297404, 2020). "Furthermore, we discovered that YAP1 was positively correlated with the majority of EMT markers in PDAC tissues from the cancer genome atlas (TCGA) dataset." (PMID 32894161, 2020). "In addition, expression of YAP1 was inversely correlated with E-cad in cancer specimens (Spearman’s r = − 0.238, P < 0.001), but was positively associated with Vim expression (Spearman’s r = 0.219, P < 0.001)." (PMID 32894161, 2020). "Through pharmacologic or genetics inhibition of YAP1 could not only suppress malignant transformation of relevant cancers but also provide an improved measure of drug sensitivity to chemotherapy." (PMID 33123286, 2020). "Interestingly, YAP1 has been implicated in both oncogenic KRAS-dependent and -independent cancer-promoting activities 11-14, suggesting it plays a critical role across a wide range of cancers." (PMID 32292505, 2020). "Undoubtedly, YAP1/TAZ is a potential therapeutic target for cancer and cardiac disease." (PMID 32390875, 2020).
cancer (continued). "Receptor for hyaluronic acid-mediated motility is transcriptionally regulated through Yes-associated protein 1 (YAP1) and transcriptional co-activator with PDZ-binding motif (TAZ), whose own expressions are found to be elevated in cancer cells during their malignant progression." (PMID 33043017, 2020). "In humans, the YAP1 locus was found to be amplified in different types of cancer." (PMID 32737120, 2020). "YAP1 plays a part in several cellular processes and cancers." (PMID 33023613, 2020). "The mean cytoplasmic YAP1 immunoreactivity score in residual cancer cells in the CHT group was significantly higher than that in the NNA (4.71 ± 0.20 vs. 2.57 ± 0.26, respectively, p < 0.001) and NHT groups (4.71 ± 0.20 vs. 2.90 ± 0.32, respectively, p < 0.001)." (PMID 32293349, 2020). "However, the role of YAP1 in carcinogenesis is complex, with a recent study showing that the activation of YAP1 in peritumoral tissues has an inhibitory effect in cancer." (PMID 33178690, 2020). "Many inhibitory immune checkpoint genes are upregulated in the SOH subgroup, suggesting that YAP1/TAZ may induce the resistance of cancer cells to host immune response in GBM." (PMID 32717825, 2020). "However, if SLC35B4 is a context-dependent target gene or a general target gene of YAP1 still needs to be further confirmed in multiple cancers in the future." (PMID 31175271, 2019). "Importantly, they found that YAP1 gene was amplified in cancer cells derived from the EMT cluster, and YAP1 protein was the most significantly differentially expressed protein that distinguished the EMT cluster from other sub-groups." (PMID 30840887, 2019). "Nuclear YAP1 was shown to promote cancer cell survival by activating Survivin expression." (PMID 30956771, 2019). "One of these is YAP1, a transcriptional regulator and the main effector of the Hippo pathway, which normally regulates cellular proliferation and differentiation but also promotes malignant phenotypes and drug resistance in various cancers." (PMID 31137841, 2019). "For example, in a stromal cell, YAP1 upregulates transcription of myofibroblast marker, such as CYR-61 and CTGF for activating cancer-associated fibroblast that is required for remodeling cancer stroma." (PMID 31137841, 2019). "A better understanding of this process and how it is regulated could yield new insights into how Hippo activity is modulated in developing tissues and provide avenues for therapeutic strategies that aim to reduce Yap1 activity and levels in human cancers." (PMID 32010696, 2019). "YAP1 protein has emerged as a promising therapeutic target in varies of cancer types." (PMID 31601234, 2019). "The results might suggest nuclear YAP1 plays an important role in cancer, but it still needs more studies to be demonstrated furthermore." (PMID 31613226, 2019). "Further evidence suggests a pivotal role for YAP1 in the development of cancer drug resistance." (PMID 31543507, 2019). "It controls several cancer-associated genes, such as mammalian target of rapamycin (mTOR), hepatocyte growth factor receptor c-Met, the kinase p21-activated kinase 4 (PAK4), and the Notch regulator Yes-associated protein 1 (YAP1)." (PMID 31805631, 2019). "YAP1 signaling was pivotal for cancer cell proliferation, metastasis and drug resistance." (PMID 31848326, 2019). "Subsequently, many studies demonstrated that YAP1 was a negative prognostic marker in many tumors and promoted epithelial-mesenchymal transition, which indicated that YAP1 might induce cancer metastasis and invasion." (PMID 31613226, 2019). "Numerous studies have shown that overexpression of the YAP1 gene is found in various human cancers." (PMID 30868052, 2019). "YAP1, as the main effector of Hippo pathway, plays a critical role in the development of cancers, standing at the cross point of different signaling pathways, mediated by upstream effectors and then regulating targets in collaboration with other transcription factors." (PMID 31613226, 2019).
cancer (continued). "YAP1 is a transcriptional co-activator in the Hippo signaling pathway, and YAP1-induced transcriptional responses are essential in proliferation and metastasis of cancer cells." (PMID 30925892, 2019). "Interestingly, the subgroup of ccRCC patients in whom cytoplasmic presence of YAP1 in cancer cells was observed exhibited the strongest correlation with patients' poor prognosis." (PMID 29850494, 2018). "Secondly, YAP1 activation in normal tissue has the key role in cell trans- differentiation, but in cancer tissue, there may be different signals for YAP1 activation to induce CSCs features." (PMID 30234141, 2018). "The meta-analyses of 20 IHC studies related to YAP1 presence in cancer cells showed that nuclear as well as overall (nuclear and cytoplasmic) localization of this protein correlated with poorer overall survival (OS) time and disease-free survival time (DFS) in numerous types of cancer." (PMID 29850494, 2018). "Moreover, YAP1 can also confer cancer stem cell properties by upregulating SOX9 and can inhibit skeletal development and bone repair by affecting chondrocyte proliferation." (PMID 29700328, 2018). "Our finding is supported by the results of several studies, which suggest that in the cytoplasm of cancer cells YAP1 may play a role as a molecular factor inducing more aggressive cancer behavior." (PMID 29850494, 2018). "Our proposed role for Yap1 as a pro-survival factor in ESCs is consistent with other studies done in cancer or epithelial contexts, but our work is the first study to show such a contextual, differentiation-specific role for Yap1 in ESCs." (PMID 30561326, 2018). "Hippo-YAP1 signalling is a cancer-related pathway that inhibits cell proliferation and metastasis." (PMID 29899399, 2018). "Previous studies have demonstrated that YAP1/TAZ play crucial roles in cancer stem cells." (PMID 28782275, 2018). "Importantly, several studies have demonstrated that YAP1 is correlated with cancer stem cells (CSCs) like properties." (PMID 30234141, 2018). "From the therapeutic point of view, treating LIF-high NPC cells with AZD0530 may potentially prevent cancer dissemination by inactivating YAP1-SRC-focal adhesion signaling." (PMID 30504771, 2018). "AMOT promotes either YAP1 nuclear localization or cytoplasmic retention in different cancer types." (PMID 29650031, 2018). "Although these data cannot tell us precisely whether VASP modulates YAP1/TAZ at downstream or upstream of RhoA, the data are of clinical significance given the high relevance of the GPCR-RhoA-YAP1/TAZ signaling cascade in cancer progression and metastasis." (PMID 29872721, 2018). "WT and LIF+/− cancer cells expressed medium to high levels of YAP1." (PMID 30504771, 2018). "Thus, Hippo pathway agonists that activate MST1/2 and LATS1/2 kinases and inhibit YAP1 activation in cancer cells have been identified as candidate therapeutic agents." (PMID 29565815, 2018). "Therefore, we decided to assess the immunoreactivity of LATS1 and YAP1 proteins within the cancer and normal kidney tissue of patients with ccRCC." (PMID 29850494, 2018). "We also show that unrestrained YAP1 acts as an oncogenic driver in HNSCC, and that targeting YAP1 may represent an attractive precision therapeutic option for cancers harboring genomic alterations in the FAT1 tumor suppressor genes." (PMID 29985391, 2018). "Furthermore, YAP1 and Slug have important roles in promoting cancer cell invasion and migration in vitro, and silencing YAP1 inhibits NSCLC formation and EMT in vivo." (PMID 29700328, 2018). "In the majority of cancers, WWTR1 and YAP1 have been reported to lack mutations." (PMID 30167083, 2018). "Since addiction to anti-apoptotic factors is a defining characteristic of cancer cells, the regulation mechanisms we have elucidated may be broadly applicable to how Yap1 promotes tumorigenesis." (PMID 30561326, 2018). "The TEAD‐YAP1 complex is crucial for YAP1 function in various cancers." (PMID 28782275, 2018).